RNU6-753P (RNA, U6 small nuclear 753, pseudogene)
Gene: Small nuclear RNA gene on chromosome 1 (38,396,659 to 38,396,765, forward strand). Ensembl gene ENSG00000200796.
Homologues: Orthologues: chimpanzee U6 (100% identical), macaque U6 (96% identical), pig U6 (79% identical), dog U6 (78% identical). Paralogues in human: RNU6-1031P (89% identical), RNU6-1316P (88% identical), RNU6-144P (88% identical), RNU6-211P (88% identical), RNU6-1040P (87% identical), RNU6-1145P (87% identical), RNU6-16P (87% identical), RNU6-181P (87% identical), RNU6-310P (87% identical), RNU6-393P (87% identical), RNU6-940P (87% identical), RNU6-961P (87% identical), and 1288 more.